SLC9C2 (solute carrier family 9 member C2 (putative))
Description:
Involved in pH regulation.
Synonyms: SLC9A11; MGC43026; NHE11
Tractability: Antibody: UniProt predicts a signal peptide or a membrane-spanning region; its Gene Ontology location is reachable by antibodies, with medium confidence; the Human Protein Atlas places it where antibodies can reach.
Gene: Protein-coding gene on chromosome 1 (173,500,460 to 173,603,072, reverse strand). Ensembl gene ENSG00000162753.
Subcellular location: Membrane
Subcellular location (Human Protein Atlas): Plasma membrane; Nuclear speckles
Pathways (Reactome):
Transport of small molecules: Stimuli-sensing channels
Gene Ontology:
Molecular function: antiporter activity; sodium:proton antiporter activity
Biological process: regulation of intracellular pH; sodium ion import across plasma membrane; monoatomic cation transport; proton transmembrane transport; transmembrane transport
Cellular component: plasma membrane; membrane
Genetic constraint (gnomAD): Loss-of-function variants: 49 observed, 88.03 expected, observed/expected ratio (o/e) 0.56, 90% interval 0.44 to 0.71. The upper end of that interval is the gene's LOEUF score, 0.71, which puts it in group 2 of 6, group 1 being the genes least tolerant of losing a copy. Missense variants: 752 observed, 970.28 expected, observed/expected ratio (o/e) 0.78, 90% interval 0.73 to 0.82. Synonymous variants: 265 observed, 312.09 expected, observed/expected ratio (o/e) 0.85, 90% interval 0.77 to 0.94.
Homologues: Orthologues: chimpanzee SLC9C2 (99% identical), macaque SLC9C2 (90% identical), rabbit SLC9C2 (72% identical), dog SLC9C2 (71% identical), mouse SLC9C2 (68% identical), Drosophila melanogaster Nhe2 (11% identical), Drosophila melanogaster Nhe3 (8% identical), Caenorhabditis elegans nhx-2 (8% identical), Caenorhabditis elegans nhx-4 (7% identical), Caenorhabditis elegans nhx-6 (7% identical), Caenorhabditis elegans nhx-5 (7% identical). Paralogues in human: SLC9C1 (28% identical), SLC9A1 (12% identical), SLC9A5 (11% identical), SLC9A2 (11% identical), SLC9A4 (11% identical), SLC9A3 (10% identical), SLC9A7 (9% identical), SLC9A6 (9% identical), SLC9A9 (9% identical), SLC9A8 (7% identical).
Diseases named in the same sentence as SLC9C2 in open-access papers:
SLC9C2 is named in the same sentence as 7 diseases in open-access papers, as found by Europe PMC text mining. Sharing a sentence is not in itself a finding about the gene and the disease. The quoted sentences say what the papers report.
periodontitis (2 papers, 2019 to 2022). An acute or chronic inflammatory process that affects the tissues that surround and support the teeth. "Currently, there is a lack of knowledge about the function of this molecule; however, in the context of periodontitis, a chronic inflammatory disease, the association between the SLC9C2 gene and systolic and diastolic blood pressure has been described." (PMID 36297433, 2022). "A total 10,268 SNPs of ten targeted periodontitis genes were analyzed among 2649 SNPs in five genes (TENM2, LDLRAD4, SLC9C2, MFSD1, and A2BP1), and their statistical differences (p < 0.05) are listed." (PMID 30547318, 2019). "Specifically, if any one of TENM2, A2BP1, LDLRAD4, SLC9C2, or MFSD1 was observed in the patients with periodontitis, obesity and blood pressure have to be treated simultaneously." (PMID 30547318, 2019). "Therefore, if any of TENM2, A2BP1, LDLRAD4, SLC9C2, and MFSD1 is detected in the patients with periodontitis, obesity and blood pressure have to be treated simultaneously." (PMID 30547318, 2019).
high blood pressure (1 paper, 2019). "Also, elevated levels of LDLRAD4, SLC9C2, and MFSD1 were observed in the patients with high blood pressure." (PMID 30547318, 2019).
Obesity (1 paper, 2019). Accumulation of substantial excess body fat. "The present study discovered that five genes (A2BP1, TENM2, LDLRAD4, SLC9C2, and MFSD1) were associated with metabolic traits such as obesity and high blood pressures." (PMID 30547318, 2019).
SLC9C2 also shares sentences with these, for which no sentence is quoted: heart failure (2 papers); diabetes (1); Infertility (1); type 2 diabetes (1).